MIR3606 (microRNA 3606)
Synonyms: hsa-mir-3606; mir-3606
Gene: MicroRNA gene on chromosome 2 (188,995,630 to 188,995,692, forward strand). Ensembl gene ENSG00000284180.
Homologues: Orthologues: chimpanzee MIR3606 (100% identical).